IGKV2-24 (immunoglobulin kappa variable 2-24)
Description:
V region of the variable domain of immunoglobulin light chains that participates in the antigen recognition. Immunoglobulins, also known as antibodies, are membrane-bound or secreted glycoproteins produced by B lymphocytes. In the recognition phase of humoral immunity, the membrane-bound immunoglobulins serve as receptors which, upon binding of a specific antigen, trigger the clonal expansion and differentiation of B lymphocytes into immunoglobulins-secreting plasma cells. Secreted immunoglobulins mediate the effector phase of humoral immunity, which results in the elimination of bound antigens. The antigen binding site is formed by the variable domain of one heavy chain, together with that of its associated light chain. Thus, each immunoglobulin has two antigen binding sites with remarkable affinity for a particular antigen. The variable domains are assembled by a process called V-(D)-J rearrangement and can then be subjected to somatic hypermutations which, after exposure to antigen and selection, allow affinity maturation for a particular antigen.
Synonyms: A23; IGKV224
Gene: Immunoglobulin variable (V) gene on chromosome 2 (89,176,328 to 89,177,160, reverse strand). Ensembl gene ENSG00000241294.
Subcellular location: Secreted; Cell membrane
Gene Ontology:
Biological process: immune response
Cellular component: extracellular region; immunoglobulin complex; plasma membrane
Homologues: Paralogues in human: IGKV2D-24 (98% identical), IGKV2-30 (88% identical), IGKV2D-30 (87% identical), IGKV2D-29 (83% identical), IGKV2D-40 (82% identical), IGKV2-28 (82% identical), IGKV2D-28 (82% identical), IGKV2D-26 (76% identical), IGKV2-40 (69% identical), IGKV4-1 (57% identical), IGKV3-20 (56% identical), IGKV3-11 (55% identical), and 81 more.